EBAG9 (estrogen receptor binding site associated antigen 9)
Description:
May participate in suppression of cell proliferation and induces apoptotic cell death through activation of interleukin-1-beta converting enzyme (ICE)-like proteases.
Synonyms: RCAS1; EB9; PDAF
Tractability: Antibody: UniProt predicts a signal peptide or a membrane-spanning region. PROTAC: ubiquitination databases record sites on it; its protein half-life has been measured.
Gene: Protein-coding gene on chromosome 8 (109,539,711 to 109,570,072, forward strand). Ensembl gene ENSG00000147654.
Subcellular location: Golgi apparatus membrane
Subcellular location (Human Protein Atlas): Golgi apparatus
Pathways (Reactome):
Signal Transduction: Estrogen-dependent gene expression
Gene Ontology:
Molecular function: protein binding; peptidase activator activity involved in apoptotic process
Biological process: regulation of cell growth; apoptotic process
Cellular component: Golgi apparatus; Golgi membrane; secretory granule
Genetic constraint (gnomAD): Loss-of-function variants: 7 observed, 19.81 expected, observed/expected ratio (o/e) 0.35, 90% interval 0.2 to 0.66. The upper end of that interval is the gene's LOEUF score, 0.66, which puts it in group 2 of 6, group 1 being the genes least tolerant of losing a copy. Missense variants: 134 observed, 174.19 expected, observed/expected ratio (o/e) 0.77, 90% interval 0.67 to 0.89. Synonymous variants: 62 observed, 58.45 expected, observed/expected ratio (o/e) 1.06, 90% interval 0.86 to 1.31.
Homologues: Orthologues: chimpanzee EBAG9 (99% identical), macaque EBAG9 (99% identical), guinea pig EBAG9 (98% identical), mouse Ebag9 (98% identical), rabbit EBAG9 (98% identical), dog EBAG9 (97% identical), pig EBAG9 (97% identical), rat Ebag9 (94% identical), tropical clawed frog ebag9 (81% identical), zebrafish ebag9 (78% identical), Drosophila melanogaster CG32536 (27% identical), Caenorhabditis elegans ZK154.4 (22% identical).
Diseases named in the same sentence as EBAG9 in open-access papers:
EBAG9 is named in the same sentence as 60 diseases in open-access papers, as found by Europe PMC text mining. Sharing a sentence is not in itself a finding about the gene and the disease. The quoted sentences say what the papers report.
breast carcinoma (7 papers, 2001 to 2018). "Estrogen receptor-binding fragment-associated antigen 9 (EBAG9) has been originally identified as an estrogen-responsive gene in breast cancer cells." (PMID 29362448, 2018). "Recently, oestrogen receptor-binding fragment associated gene 9 (EBAG9) has been identified as an oestrogen-responsive gene from a cDNA library of MCF-7 human breast cancer cell line." (PMID 15164121, 2004). "EBAG9 immunoreactivity was also associated with various clinicopathological parameters, including intratumoural infiltration of inflammatory cells, to examine the biological significance of EBAG9 in human breast carcinomas." (PMID 11742495, 2001). "Oestrogen receptor-binding fragment associated gene 9, EBAG9, is an oestrogen-responsive gene that was identified in MCF-7 human breast carcinoma cell line." (PMID 15164121, 2004). "The minimal region of overlap on 8q in our study (q23) is the location of the EBAG9/RCAS1 gene, which encodes a cancer cell-surface antigen implicated in immune escape and has recently been shown to be amplified in breast cancer." (PMID 14970871, 2004). "EBAG9 has been recently identified as an oestrogen responsive gene in MCF-7 human breast carcinoma cells." (PMID 11742495, 2001). "In this study, we examined the expression of EBAG9/RCAS1 in human breast carcinomas using immunohistochemistry and reverse transcription-polymerase chain reaction (RT-PCR)." (PMID 11742495, 2001). "This study suggests that EBAG9 is produced via ER in carcinoma cells and inhibits the intratumoural infiltration of T lymphocytes in the context of a possible endocrine–immune interaction in human breast carcinomas." (PMID 11742495, 2001). "The mRNA expression of those canonical ER-targeted genes including EFP, COX7RP and EBAG9 were induced after E2 treatment as expected in breast cancer cells, but did not change significantly after knockdown of CALML3 compared to the control." (PMID 28821270, 2017).
ovarian carcinoma (6 papers, 2004 to 2019). A malignant neoplasm originating from the surface ovarian epithelium. "Protein expression of EBAG9, as detected by immunoblotting with a polyclonal anti EBAG9 serum, was reported in ovarian cancer cell lines." (PMID 15904507, 2005). "Immunoreactive bands corresponding to EBAG9 and ERα were detected in 11 out of 12 and 10 out of 12 of ovarian cancer cell lines, respectively." (PMID 15164121, 2004). "There was a strong correlation between EBAG9 and ERα immunoreactivity in ovarian cancer tissues (P<0.0001) and cell lines in this study." (PMID 15164121, 2004). "In the present study, we examined the expression of EBAG9/RCAS1 in human epithelial ovarian cancer using immunohistochemistry, immunoblotting and reverse transcription–polymerase chain reaction (RT–PCR)." (PMID 15164121, 2004). "Immunoreactivity for EBAG9 was detected on the surface and in the cytoplasm of epithelial ovarian cancer tissues." (PMID 15164121, 2004). "A total of 90 epithelial ovarian cancer cases were examined immunohistochemically by means of the antibodies for EBAG9 and ERα." (PMID 15164121, 2004). "Immunoreactive band corresponding to EBAG9 was detected in 11 out of 12 of ovarian cancer cell lines, and was consistent with ERα expression." (PMID 15164121, 2004). "Further investigations are required to clarify the precise functions of EBAG9 in epithelial ovarian cancer." (PMID 15164121, 2004). "In conclusion, the wide distribution of EBAG9 and its relation to advanced disease suggest that this protein may play important roles in epithelial ovarian cancer." (PMID 15164121, 2004). "Therefore, in this study, we examined the expression of EBAG9 in human epithelial ovarian cancer using immunohistochemistry, reverse transcription–polymerase chain reaction (RT–PCR) and immunoblotting." (PMID 15164121, 2004). "The expression for EBAG9 and ERα was examined by immunoblotting in 12 ovarian cancer cell lines." (PMID 15164121, 2004). "Our results, together with previous reports, suggest that ovarian cancer that expresses EBAG9 may have invasive and progressive characteristics." (PMID 15164121, 2004). "However, the expression of EBAG9 and its clinical significance have not been examined in epithelial ovarian cancer." (PMID 15164121, 2004).
prostate carcinoma (5 papers, 2014 to 2024). A carcinoma that arises from epithelial cells of the prostate gland. "TM9SF1 has also been reported to interact with EBAG9 (estrogen receptor binding site associated antigen 9) and be involved in epithelial–mesenchymal transition process of prostate cancer cells." (PMID 35597784, 2022). "They demonstrated that spontaneous development of prostate cancer was supressed in a mouse EBAG9 knockout model." (PMID 38730670, 2024). "It has been recently shown that prostate cancer-derived extracellular vesicles containing EBAG9 can both promote EMT in prostate cancer cells as well as suppress the cytotoxicity of T lymphocytes." (PMID 31096701, 2019). "To investigate the role of EBAG9 in the pathophysiology of prostate cancer cells, we performed functional studies using siRNA targeting EBAG9 (siEBAG9) in androgen-sensitive LNCaP and androgen-refractory DU145 cells." (PMID 29362448, 2018). "In prostate cancer cells, EBAG9 regulated cell migration and EMT-related gene expression through the interaction with TM9SF1." (PMID 29362448, 2018). "In this study, Ebag9KO mice crossed with TRAMP mice demonstrated that EBAG9 plays a crucial role in prostate cancer development." (PMID 29362448, 2018). "TM9SF1 and EBAG9 cooperatively regulate prostate cancer cell migration by modulating the expression of genes involved in epithelial-mesenchymal transition (EMT)." (PMID 29362448, 2018). "In this study, we showed that spontaneous development of prostate cancer was repressed in a model of Ebag9 knockout mice crossed with transgenic adenocarcinoma of the mouse prostate (TRAMP) mice." (PMID 29362448, 2018). "ERα-mediated regulation of oncogenic TMPRSS2-ERG fusion and oestrogen regulation of the EBAG9 gene, which confirms aggressive behaviour of prostate cancer, are noted examples that suggest a functional ERα-signalling pathway exists in prostate cancer." (PMID 25415230, 2014). "The gain- and loss-of-function studies of EBAG9 indicate that EBAG9 could modulate the gene expression associated with EMT, which may contribute to prostate cancer progression." (PMID 29362448, 2018). "Western blot analysis detected endogenous expression of EBAG9 protein in the EVs prepared from conditioned media of LNCaP-Vector and LNCaP-EBAG9 cells (lower signals), indicating that EBAG9 is primarily secreted from prostate cancer cells." (PMID 29362448, 2018). "In addition, EVs, which contained overexpressed EBAG9 protein, increased the migration of prostate cancer cells." (PMID 29362448, 2018). "Notably, we showed that cancer-derived EVs contain EBAG9 protein, which promotes EMT of prostate cancer cells, as well as represses the cytotoxicity of T cells." (PMID 29362448, 2018). "This study revealed that EBAG9 modulates the expression of EMT-related genes containing VIM, SNAI1, and SNAI2 in prostate cancer cells, suggesting that EBAG9 could stimulate cancer progression and invasion through EMT pathway." (PMID 29362448, 2018).
female infertility (3 papers, 2023 to 2025). Diminished or absent ability of a female to achieve conception. "For example, the EBAG9 locus associated with female infertility is under directional selection, perhaps because EBAG9 plays a role in the adaptive immune memory response to infection." (PMID 40229599, 2025). "While we found no genome-wide signature of directional selection against infertility, we observed extreme SDSs (in the highest 99.75th percentile of SNPs within 10 kb of a GWAS catalog variant) at the EBAG9 locus associated with female infertility, indicating recent positive selection." (PMID 40229599, 2025). "For example, the EBAG9 locus associated with female infertility is under directional selection, perhaps because EBAG9, which is highly expressed in CD34-/CD41+/CD42+ megakaryocytes, plays a role in T-cell mediated cytotoxicity as part of the adaptive immune memory response to infection." (PMID 38562841, 2024). "The evolutionary persistence of female infertility-risk alleles in EBAG9 may be explained by recent directional selection." (PMID 38562841, 2024). "Among the remaining 18 variants in non-OMIM genes, we highlight CASP7 (adult-onset cataract) and EBAG9 (female infertility)." (PMID 36653560, 2023).
Infertility (3 papers, 2024 to 2025). "We found evidence at non-hormonal, pleiotropic, infertility loci for recent directional selection (EBAG9) and balancing selection (GREB1, INHBB, PCDH15)." (PMID 38562841, 2024).
leukemia (2 papers, 2014 to 2022). A malignant (clonal) hematologic disorder, involving hematopoietic stem cells and characterized by the presence of primitive or atypical myeloid or lymphoid cells in the bone marrow and the blood. "Since miHag specific alloresponses after donor lymphocyte infusions are of substantial clinical relevance in graft-versus-leukemia effects, we conclude that EBAG9 defines a crucial checkpoint for the cytolytic capacity of CD8+ T cells and may hence be suitable for therapeutic exploitation." (PMID 35821635, 2022).
placental abruption (2 papers, 2005 to 2021). Vaginal bleeding preceding the 20th week of gestation. "Receptor-binding cancer antigen expressed on SiSo cells (RCAS1, EBAG9) is a type II membrane protein described in the context of placental abruption." (PMID 34205566, 2021).
chronic leukemia (1 paper, 2022). A slowly progressing leukemia characterized by a clonal (malignant) proliferation of maturing and mature myeloid cells or mature lymphocytes. "In summary, the Ebag9-associated cytolytic enhancer model provided insight into CD8+ T cell programming, either when stimulated briefly or when challenged by a chronic leukemia burden." (PMID 35482418, 2022).
chronic lymphocytic leukemia (1 paper, 2022). "This property endowed Ebag9–/– mice with extended control of Tcl-1 oncogene–induced chronic lymphocytic leukemia progression." (PMID 35482418, 2022).
invasive ductal carcinomas (1 paper, 2001). "EBAG9 immunoreactivity was detected in the entire surface and cytoplasm of carcinoma cells in 82 out of 91 invasive ductal carcinomas (90.1%)." (PMID 11742495, 2001).
Wilms tumor (1 paper, 2024). An embryonal neoplasm characterized by the presence of epithelial, mesenchymal, and blastema components. "The identified prognostic genes, particularly GRAMD1A, SPR, EBAG9, RBM47, and RIDA, offer significant potential as both prognostic biomarkers and therapeutic targets for improving personalized treatment in Wilms tumor patients." (PMID 39659787, 2024).
tumor (30 papers, 2001 to 2025). "CD8+ memory commitment was analyzed in Ebag9-deficient mice that exhibited enhanced tumor cell lysis." (PMID 35482418, 2022). "EBAG9 was originally described as a novel tumor associated antigen with a functional role in tumor-immune interactions." (PMID 15904507, 2005). "This raised the question if EBAG9 is tumor-specific and mediates apoptosis itself or through O-linked glycans generated, among them the cognate 22-1-1 antigen Tn." (PMID 15904507, 2005). "By facilitating exocytosis of granzyme A, EBAG9 silencing may compensate for a loss in therapeutic index, which may accompany engineering efforts aimed at mitigating on-target/off-tumor effects through reduction of CAR-antigen affinity." (PMID 35821635, 2022). "Knockdown of EBAG9 led to an accelerated elimination of the BCMA-expressing tumor cell lines DOHH-2 and JeKo-1 (BCMAlow)." (PMID 35821635, 2022). "Considerably fewer EBAG9-silenced human CAR T cells were needed for tumor growth control in a xenotransplantation model." (PMID 35821635, 2022). "By comparing the single-cell transcriptomes of CD8+ T cells responding to tumor cell vaccination, we found differential distribution of subpopulations between Ebag9+/+ and Ebag9–/– T cells." (PMID 35482418, 2022). "We validated that silencing of EBAG9 is not only adequate to improve the anti-tumor response of conventional but also of CAR-modified T cells, without compromising the safety of CAR T cell therapy." (PMID 35821635, 2022). "We examined the extent to which EBAG9 downregulation affected the anti-tumor response of BCMA CAR T cells in a NOD.Cg-Prkdcscid Il2rg tm1 Wji/Szj (NSG) mouse xenotransplantation model." (PMID 35821635, 2022). "Collectively, EBAG9 silencing endows BCMA CAR T cells with a considerably improved capacity to reduce tumor growth in vivo, as even low numbers of killing-enhanced CAR T cells gained control over aggressive tumor progression." (PMID 35821635, 2022). "MicroRNA (miRNA)-mediated EBAG9 downregulation in transplanted cytolytic CD8+ T cells (CTLs) from immunized mice improved their cytolytic competence in a tumor model." (PMID 35821635, 2022). "Next, to avoid the inherent flaws of transplantable tumors, we examined the functional consequences of Ebag9-governed cytolytic strength in an autochthonous tumor model." (PMID 35482418, 2022). "Two other significantly downregulated genes, HARS and EBAG9, reduce cytotoxic activity of T lymphocytes and block tumor T cell infiltration." (PMID 34654826, 2021). "In Renca syngeneic transplantation renal cancer models, we demonstrated that EBAG9 overexpression stimulated the tumor formation of syngeneic transplantation model." (PMID 29362448, 2018). "EBAG9 in cancer cells suppresses T-cell infiltration into tumor in vivo, whereas that in host immune cells functions as a limiter for T-cell cytotoxicity." (PMID 29362448, 2018). "We infer that tumor-derived EV-mediated EBAG9 protein is a critical factor that potentially facilitates tumor progression by negatively modulating immune cells in microenvironment." (PMID 29362448, 2018). "EBAG9 would transfer to immune T cells through EVs and negatively regulate tumor surveillance in host cells." (PMID 29362448, 2018). "RCAS1 is a protein that is encoded in humans by the EBAG9 gene and participates in the immunomodulatory effects of tumor cells." (PMID 25674852, 2015). "Almost all tumor cell lines expressed EBAG9 in varying amounts, indicated by a characteristic double band and stained with our polyclonal anti EBAG9 serum." (PMID 15904507, 2005). "This conclusion is substantiated by only partial correlation between endogenous EBAG9 protein levels and the corresponding expression profiles for the 22-1-1 antigen in human tumor cell lines, as determined by immunoblotting or flow cytometry, respectively." (PMID 15904507, 2005).